LINC00630 (long independently transcribed non-coding RNA 630)
Gene: Long non-coding RNA gene on chromosome X (102,720,701 to 102,997,186, forward strand). Ensembl gene ENSG00000223546.
Diseases named in the same sentence as LINC00630 in open-access papers:
LINC00630 is named in the same sentence as 10 diseases in open-access papers, as found by Europe PMC text mining. Sharing a sentence is not in itself a finding about the gene and the disease. The quoted sentences say what the papers report.
non-small cell lung carcinoma (3 papers, 2017 to 2021). A group of at least three distinct histological types of lung cancer, including non-small cell squamous cell carcinoma, adenocarcinoma, and large cell carcinoma. "Here we report the discovery of a critical role for the linc00630 in the development of Non-Small-Cell Lung Cancers (NSCLCs)." (PMID 28473661, 2017). "Long intergenic non-protein coding RNA 630 (LINC00630) is ubiquitously expressed in bone marrow, lymph nodes and 25 other tissues and is considered a biomarker for various cancers, such as non-small-cell lung cancer and colorectal cancer." (PMID 34106877, 2021).
pulpitis (2 papers, 2021 to 2023). Inflammation of the dental pulp. "Three lncRNAs (i.e., XIST, MIR155HG, and LINC00630) are identified to be key factors involved in the ceRNA network of pulpitis." (PMID 33777260, 2021).
liver cancer (1 paper, 2023). An epithelial or non-epithelial malignant neoplasm that arises from the liver. "LINC00630 is a promising molecular target for liver cancer treatment." (PMID 37240281, 2023). "LINC00630 increases E2F1 binding to the CDK2 promoter region, stimulates CDK2 transcription, and thereby accelerates the malignant development of liver cancer." (PMID 37240281, 2023).
lung carcinoma (1 paper, 2017). "It was determined that linc00630 expression was elevated to in 6 lung cancer cell lines, whereas linc00630expression was lower in H1299 and higher in A549 than that in human bronchial epithelial cells (HBEs)." (PMID 28473661, 2017).
squamous carcinoma (1 paper, 2017). "Linc00630 was expressed extensively in NSCLC cell lines, we performed qRT-PCR analysis to determine the expression level of linc00630 in 8 human NSCLC cell lines which include both squamous carcinoma and adenocarcinoma." (PMID 28473661, 2017).
cancer (3 papers, 2017 to 2022). A tumor composed of atypical neoplastic, often pleomorphic cells that invade other tissues. "We determined that the high expression level of linc00630 was significantly associated with tumor size, TNM tumor stage, Lymph node status positive and cancer-related death." (PMID 28473661, 2017).
tumor (1 paper, 2017). "Linc00630 expression was higher in metastatic tumor tissues than in normal tissues, suggesting its potential role in tumor metastasis." (PMID 28473661, 2017). "With the higher level confirmed in a separate cohort 90 NSCLCs patients, overexpressed of linc00630 also positive associated with tumor size, TNM tumor stage, lymph node status positive and overall patient outcomes." (PMID 28473661, 2017). "Seven weeks after post-injection, linc00630 overexpression group dramatically increased tumor metastasis, which was determined by the metastasis loci numbers in Hemotoxylin and Eosin staining (H&E) staining, relative to the control group." (PMID 28473661, 2017). "In conclusion, we characterized the lncRNA linc00630 as a novel tumor oncogene in NSCLC." (PMID 28473661, 2017). "Linc00630 expression was positively correlated with TNM stage, tumor size and was negatively correlated with metastasis and overall survival (OS) time." (PMID 28473661, 2017).
LINC00630 also shares sentences with these, for which no sentence is quoted: adenocarcinoma (1 paper); cholangiocarcinoma (1); colorectal cancer (1).